IL33 (interleukin 33)
Diseases named in the same sentence as IL33 in open-access papers (continued):
Sharing a sentence is not in itself a finding about the gene and the disease.
gout (continued). "Interestingly, when compared with low serum HDL levels, the gout patients with high-HDL levels showed an increased IL-33 expression (328.9 ± 231.5 versus 154.2 ± 97.35 pg/mL, p = 0.01)." (PMID 27579324, 2016). "The aim of this study was to investigate the associations between genetic variants in the interleukin (IL) and interleukin receptor (ILR) genes IL-33, IL-1RL1, IL-23R, and signal transducer and activator of transcription 4 (STAT4) and susceptibility to gout in Chinese Han male individuals." (PMID 26399911, 2015). "Thus, IL-33 may directly promote neutrophil influx by acting on ST2 expressed in neutrophils during gout via the paracrine mechanism." (PMID 33204337, 2020). "Therefore, our results suggest that macrophage may be among one of the cellular sources for IL-33 overproduction during gout." (PMID 33204337, 2020). "We set to study whether IL-33 was involved in mechanical allodynia of the mouse gout model." (PMID 33204337, 2020). "Taken together, our data demonstrated that the increased levels of IL-33 may be a cause of self-negative regulation which inhibits the development of MSU-induced inflammation, and IL-33 might offer an alternative therapy to our current approaches of managing gout." (PMID 30863362, 2019). "In addition, the role of IL-33 in the gout patients with kidney injury was analyzed." (PMID 27579324, 2016). "Interestingly, it is noted that IL-33 was associated with HDL and CRE in gout, suggesting that the IL-33 may play a beneficial role in the pathogenesis of gout." (PMID 27579324, 2016). "However, there is little information regarding the role of IL-33 in gout." (PMID 27579324, 2016). "Thus, IL-33 might play a protective role in the kidney injury of gout through regulating lipid metabolism." (PMID 27579324, 2016). "This is in line with the predominant neutrophilic inflammation induced by IL‐33 in the skin and peritoneal cavity and the ability of MAB‐mR3 to suppress neutrophils in a monosodium urate (MSU) crystal‐induced model of gout." (PMID 35986608, 2023). "In all, our study demonstrated a previous unidentified role of IL-33/ST2 in mediating pain hypersensitivities and inflammation in a mouse gout model through promoting neutrophil-dependent ROS production and TRPA1 channel activation." (PMID 33204337, 2020). "IL-33 promoted neutrophil influx and triggered neutrophil-dependent ROS production via ST2 during gout, which in turn, activated transient receptor potential ankyrin 1 (TRPA1) channel in dorsal root ganglion (DRG) neurons and produced nociception." (PMID 33204337, 2020). "Neutralizing or genetic deleting IL-33 and its receptor ST2 significantly ameliorated pain hypersensitivities and inflammation in the mouse gout model." (PMID 33204337, 2020). "We further found that IL-33/ST2 mediates pain hypersensitivity and inflammation in the mouse gout model through promoting neutrophil-dependent ROS production and TRPA1 channel activation." (PMID 33204337, 2020). "Thus, IL-33 might serve as a promising therapeutic target for gout." (PMID 30863362, 2019). "Moreover, genetically deleting IL-33 and its receptor ST2 significantly ameliorated pain hypersensitivity in a mouse gout model." (PMID 35265208, 2022). "Our study suggests that targeting IL-33/ST2 signaling may represent a novel therapeutic approach to ameliorate pain and inflammation in gout." (PMID 33204337, 2020). "We reason here that IL-33, after being released from macrophages, may act in an autocrine manner to induce CXCL1, CCL3 and IL-1β production via ST2 in macrophages during gout." (PMID 33204337, 2020). "Consistent with our previous study, an increased expression of IL-33 was observed in the sera of gout patients compared with healthy control (data not shown)." (PMID 30863362, 2019). "Although the cytokine secretion by macrophage can be enhanced by IL-33, in our study gout patients with no kidney injury showed a high IL-33 expression." (PMID 27579324, 2016).
gout (continued). "Although the cytokine secretion by macrophage can be enhanced by IL-33, in our study IL-33 was found increased in gout patients with no kidney injury." (PMID 27579324, 2016). "The serum IL-33 expression was predominantly increased in gout patients compared to healthy controls, and the IL-33 levels were higher in patients without kidney injury." (PMID 27579324, 2016). "The genetic distributions of rs3939286 in IL-33, rs13015714 in IL-1RL1, rs10889677 in IL-23R, and rs7574865 in STAT4 were detected in 1100 men with gout and 1227 ethnically matched controls, using Taqman allelic discrimination real-time polymerase chain reaction (PCR)." (PMID 26399911, 2015). "The production and function of cytokines may be affected by polymorphisms in the functional regions of their genes, suggesting that IL-33, IL-1RL1, IL-23R, and STAT4 may be candidate genes for the inflammatory pathogenesis of gout." (PMID 26399911, 2015). "Therefore, we began to explore whether IL-33/ST2 could have any effect on endogenous ROS production and oxidative stress level under gout condition." (PMID 33204337, 2020). "However, the participation of other cell types, such as fibroblasts, epithelial cells, etc. in IL-33 production under gout condition cannot be rule out and needs to be further tested." (PMID 33204337, 2020). "Interestingly, in our present study, although the level of IL-33 expression was increased in the gout patients and positively correlated with inflammatory marker CRP, the exogenous IL-33 treatment significantly inhibited the development of inflammation induced by MSU administration." (PMID 30863362, 2019). "Our study here presented a new clue for the self-limiting acute gout, and the increased IL-33 expression in gout patients might be a negative feedback mechanism on MSU-induced inflammation." (PMID 30863362, 2019). "Furthermore, we observed that the gout patients with renal injury showed lower IL-33 levels (median 114.9 pg/mL: 31.3–447.8) when compared with gout patients without renal injury (median 299.5 pg/mL: 57.9–741.3) (p = 0.027)." (PMID 27579324, 2016). "However, the role of IL-33 in gout patients has not been described until now." (PMID 27579324, 2016). "Our data demonstrated that increased IL-33 expression in gout patients might be a negative feedback mechanism on the MSU-induced inflammation response, because the inflammatory cytokine IL-1β production and the number of neutrophils were both markedly decreased in IL-33-treated mice." (PMID 30863362, 2019).
injury (15 papers, 2013 to 2025). Damage inflicted on the body as the direct or indirect result of an external force, with or without disruption of structural continuity. "In a remarkably similar fashion, when considering the setting of human LT, we previously reported that IL-33 release at reperfusion was positively correlated with cardinal features of early liver injury-associated disorders after LT." (PMID 37228593, 2023). "In conclusion, our findings established a pivotal role for IL-33/ST2 in regulating the activation of cGAS/STING in APAP-induced liver injury." (PMID 37081450, 2023). "In order to provide evidence that the EtOH with LI group arrived at the emergency room afflicted with latent liver injury we analyzed serum IL-33 (as a DAMP), or alarmin levels." (PMID 30859103, 2019). "Although the findings obtained do not provide evidence of definitive pathway activation, they may suggest a modest modulatory effect of quercetin on the IL-33/ST2 axis following traumatic cardiac injury." (PMID 41268524, 2025). "Besides, in models of traumatic brain injury, IL‐33 has been demonstrated to inhibit the occurrence of autophagy and modulate brain injury." (PMID 37904695, 2023). "Next, we explored whether IL-33 can ameliorate brain damage in vivo using a neonatal mouse HI brain injury model." (PMID 32859229, 2020). "Our study related to specific EV “barcodes,” and using IL-33 as an indicator of alcohol-related liver injury, requires further observations using a larger cohort of trauma patients with or without liver injury due to alcohol abuse or other causes of liver injury." (PMID 30859103, 2019). "Moreover, transient release of endogenous IL-33 has been reported after mechanical skin injury and, because of its widespread expression in the nuclei of endothelial cells from blood vessels along the vascular tree, IL-33 can be found in almost all human organs." (PMID 31360218, 2019). "Mechanistic studies revealed that IL-33/ST2 engagement stimulates the production of neurotrophic factors from astrocytes, which in turn enhances neuronal survival in neonatal HI brain injury." (PMID 32859229, 2020).
malaria (15 papers, 2015 to 2026). Malaria is a serious and sometimes fatal disease caused by a parasite that commonly infects a certain type of mosquito which feeds on humans. "By comparison, the alarmin IL-33, which has been shown to be associated with protection from complicated malaria, was significantly decreased in the spleens of Pb-infected dams." (PMID 40470930, 2025). "It has been observed that clinical or severe malaria is associated with increased levels of pro-inflammatory cytokines, including IL-1β, IL-6, IL-8, IL-10, IL-12, IL-13, IL-31, IL-33, and TNF-α." (PMID 39204168, 2024). "One such cytokine, IL-33, has recently been associated with pulmonary edema in severe malaria cases in Southeast Asian patients and was found to be positively correlated with neutrophils and activated monocytes." (PMID 27926944, 2016). "It has been observed that TNF-α, IL-31, and IL-33 are associated with clinical or severe malaria." (PMID 39204168, 2024). "Ultimately, IL-33's importance in these processes remains speculative and associative in the context of malaria, providing rationale to further explore and identify the mechanisms and activities of IL-33 during the initial malarial infection." (PMID 32363166, 2020). "It will be of interest to use the mouse model of malaria-associated ALI/ARDS to investigate if IL-33 indeed has a role in PbA-induced lung pathologies and to examine what the molecular and immune mechanisms underlying the changes may be and how they can be prevented or controlled." (PMID 27926944, 2016). "Plasma IL-33 concentrations are higher in patients with severe malaria than in patients with uncomplicated malaria and infection-free controls, suggesting that IL-33 is associated with the onset of severe malaria." (PMID 36362246, 2022). "The only prior study of IL-33 in human malaria showed high plasma levels of IL-33 in children with severe malaria." (PMID 35800259, 2022). "The majority of IL-33 and malaria studies were conducted in PbA-infected mice either in WT mice or in IL-33- or ST2-deficient mice." (PMID 36362246, 2022). "Bronchial IL-33 expression is significantly increased in severe malaria patients with pulmonary edema." (PMID 31871954, 2019). "Malaria patients with shock showed significantly increased bronchial IL-33 compare to other clinical manifestations." (PMID 26437894, 2015). "IL-33 signaling has also been identified as a driver of both protective and detrimental CNS immune responses to Toxoplasma gondii (where astrocytes are the primary responder to IL-33 signaling), malaria, Dengue, and Rocio viruses." (PMID 37983247, 2023). "Plasma IL-33 is rarely detected in children with severe malaria or in community children." (PMID 35800259, 2022). "The IL-33/ST2 pathway could be a pharmacological target of choice for the treatment of severe malaria." (PMID 36362246, 2022). "The fact that elevated serum histone levels have been shown to be implicated in proinflammatory responses and BBB disruption in malaria may question the role of IL-33 in these particular functions of host and parasitic histones." (PMID 36362246, 2022). "Therefore, new investigation for malaria therapeutics should consider IL-1β and IL-33 as potential targets." (PMID 36362246, 2022). "We postulate that sequestration of infected erythrocytes or merozoites liberation from schizonts could amplify IL-33 production in endothelial cells, contributing either to malaria pathogenesis or recovery." (PMID 36362246, 2022). "Endogenous and exogenous IL-33 appear to have differing effects in murine models of severe malaria." (PMID 35800259, 2022). "Additionally, IL-33 was shown to have pro-inflammatory properties during malaria, leading to an exacerbated pathology both in the respiratory and central nervous system." (PMID 32363166, 2020).
malaria (continued). "A better understanding of this differential recruitment of either pro- or anti-inflammatory immune cells in cancer models may help to explain the variable responses seen thus far in IL-33/ST2 malaria research." (PMID 32363166, 2020). "Additionally supporting a pathological role of IL-33 in malaria, a study utilizing a Plasmodium chaubadi model of infection on BALB/c mice showed that deficiency of ST2 reduced mortality, hepatocyte damage and inflammatory cytokine production." (PMID 32363166, 2020). "Likewise, a study using a P. berghei ANKA (PbA) model of infection on C57BL/6 mice showed that malaria-induced acute respiratory distress was alleviated by dexamethasone treatment, which coincided with decreased levels of serum IL-33." (PMID 32363166, 2020). "Moreover, the patients who showed co-existent clinical signs of shock in severe malaria exhibited significantly higher bronchial IL-33 expression." (PMID 26437894, 2015). "Bronchial IL-33 expression was significantly increased in severe malaria patients with PE." (PMID 26437894, 2015). "Bronchial expression of the cytokine IL-33 is increased in malaria patients with oedema, may be involved in lung injury and the pathogenesis of oedema in severe malaria." (PMID 26437894, 2015). "The cytokine IL-33 was suggested to function as an “alarmin”; in infants with severe malaria IL-33 levels were found enhanced, IL-33 concentrations in plasma correlated positively with parasite densities, and IL-33 diminished strongly following P. falciparum clearance." (PMID 25698903, 2015). "The correlation between the expression of these markers, histopathological and clinical parameters was evaluated to determine whether IL-33, any distinct subtypes of host leukocytes, γ-ENaC, and AQP-1 and -5 were associated with the development of PE in severe malaria lung injury." (PMID 26437894, 2015). "The results suggest that IL-33 may play a role in lung injury during severe malaria and lead to PE." (PMID 26437894, 2015). "In conclusion, our study in the sub-district of Bokito in rural Cameroon shows that plasma IL-33 levels were lower in children with Schistosomiasis independent of co-infection with malaria, hepatitis B or C or geohelminths." (PMID 31849991, 2019). "This indicates that IL-33 administration protects mice from ECM but not from malaria-induced hyperparasitemia and death." (PMID 25659095, 2015). "No such difference in plasma IL-33 concentration could be observed in either malaria or schistosomiasis-diseased participants." (PMID 31849991, 2019). "Furthermore, a positive correlation was found between bronchial IL-33 expression and the number of CD68 + monocytes and neutrophils, septal congestion score, WBC score, and hyaline membrane formation score, suggesting IL-33 may play-role in lung destruction in severe malaria." (PMID 26437894, 2015).
Anxiety (14 papers, 2017 to 2025). Intense feelings of nervousness, tension, or panic often arise in response to interpersonal stresses. "Mechanical ventilation, IL-33 levels, andC-reactive protein levels were independently associated with anxiety." (PMID 37712803, 2023). "These IL-33 deficient mice exhibit reduced anxiety-like behaviors, as well as deficits in social novelty recognition, despite intact sociability." (PMID 30515150, 2018). "IL-33 deficient mice display multiple behavioral deficits such as reduced anxiety and impaired social recognition." (PMID 30515150, 2018). "Deficiency of Il33 alters the expression of c-Fos proteins, an indicator of neuronal activities, in brain regions implicated in anxiety-related behaviors." (PMID 30515150, 2018). "Future studies are required to address the impact of Il33 deficiency in different brain areas at different developmental stages on anxiety-related and social behaviors." (PMID 29379874, 2017). "Given the enriched expression of IL-33 in oligodendrocyte-lineage cells and astrocytes, we assessed the impact on Il33 deficiency on anxiety-related behaviors." (PMID 29379874, 2017). "Because germ-free mice, which lack gut microbiota, have been shown to exhibit less anxiety-like behavior, IL-33 deficiency may cause anxiolytic effects and impairments of social behaviors by altering the composition of gut microbiota." (PMID 29379874, 2017). "Thus, our study suggests that Il33 deficiency impairs multiple behaviors, such as anxiety and social behaviors, by altering brain development/maturation." (PMID 29379874, 2017). "Rather, it is speculated that Il33 deficiency dysregulates the development and/or maturation of multiple neuronal circuits relevant to anxiety and social behaviors." (PMID 29379874, 2017). "Thus, our study suggested that Il33 deficiency results in multiple behavioral deficits, such as reduced anxiety and impaired social novelty recognition, possibly via dysregulated developmental and/or maturation of multiple neuronal circuits." (PMID 29379874, 2017). "To address whether IL-33 deficiency specifically influences anxiety-related behaviors, we also assessed the social behaviors of Il33−/− mice in the three-chamber social interaction test." (PMID 29379874, 2017). "Furthermore, 37 (57%) patients presented with anxiety, and only mechanicalventilation and IL-33 and CRP levels were significantly associated with this outcomein the univariate analysis.However, none of the variables were independently associated with anxiety in thissample." (PMID 37712803, 2023). "To understand the impact of Il33 deficiency on neuronal activity, we determined whether c-Fos immunoreactivity, an indicator of neuronal activity, was altered in brain regions implicated in anxiety-related behaviors." (PMID 29379874, 2017). "Overexpression of IL-33 in amygdala astrocytes has been demonstrated to directly induce anxiety-like behaviors in mice." (PMID 40108901, 2025). "Our most valuable finding was that the combination of anxiety–depressive symptoms explained 21% of the variation in IL-28A and 24% of the variation in IL-33." (PMID 37759873, 2023). "Multiple regression analysis confirmed significant relationships between IL-28A, IL-33, and neurotic symptoms in the anxiety–depressive spectrum." (PMID 37759873, 2023). "In remission, the positive correlation of sera levels of IL-33 was established with positive symptoms of excitement, suspiciousness/persecution, and hostility, but also with general symptoms of anxiety and tension." (PMID 29988422, 2018). "Assessment of neuronal activity by analyzing c-Fos expression in neurons immediately after the EPM suggested altered neuronal activities in multiple brain regions, including those related to anxiety in Il33−/− mice." (PMID 29379874, 2017).